GLS (glutaminase)
Diseases named in the same sentence as GLS in open-access papers (continued):
Sharing a sentence is not in itself a finding about the gene and the disease.
cancer (continued). "Herein, inhibitors of glutaminase, such as CB-839, have been investigated as potential therapies to target glutamine addiction in cancer cells, including GBMs." (PMID 39329757, 2024). "Glutamine is transported into cells through plasma membrane transporters (e.g., SLC1A5) and is subsequently converted to glutamate by glutaminase to fuel cancer cell growth." (PMID 38830868, 2024). "Mitochondrial enzymes, collectively known as glutaminase, satisfy the metabolic requirements of cancer cells." (PMID 38438397, 2024). "Targeting both mTORC2–ccGAS and glutaminase provides a promising strategy to eliminate quiescent resistant cancer cells." (PMID 39080411, 2024). "Glutaminolysis is a crucial process in cancer metabolism, involving the breakdown of glutamine by the enzyme glutaminase (GLS) to produce energy." (PMID 39795937, 2024). "The top hit was CB-839, a glutaminase (GLS) inhibitor that has been evaluated in clinical trials for cancer therapy." (PMID 39365851, 2024). "This original study unveiled the biological and clinical connections between the cuproptosis-related gene glutaminase (GLS) and pan-carcinoma." (PMID 38566121, 2024). "As glutamine metabolism plays an important role in various tumors, GLS has also become a promising therapeutic target in cancer treatment." (PMID 37664031, 2023). "The glutamine consumption rate increases in many cancers, promoted by glutaminase, reflecting the crucial role of glutaminolysis in tumor biology." (PMID 36851057, 2023). "CDKN2A displayed higher mutation rates across multiple cancer types (31%), and other frequently mutated genes included LRPPRC (13%), PRKAA2 (11%), VLDLR (9%), ASNS (8%), GZMA (7%), GLS (7%), TNFRSF1A (6%), PSAT1 (5%), and PRDX6 (4%)." (PMID 37534256, 2023). "Nevertheless, the GTωA pathway would be energetically more favorable for the conversion of l-glutamine to α-ketoglutarate than the GLS/GDH pathway in cancer biology (Equation is irreversible, whereas Equation is reversible)." (PMID 37627015, 2023). "Knocking down or inhibiting GLS can restrict the growth of various types of cancer cells and suppress cancer progression." (PMID 36959802, 2023). "Increased glutamine uptake, consumption and Glutaminase (GLS) dysregulation are hallmarks of many types of cancer." (PMID 40625719, 2023). "Glutaminase plays a crucial role in the metabolism of numerous cancers, including GBM, through the glutaminolysis pathway." (PMID 36831355, 2023). "Currently, there are many strategies for targeting glutamine metabolism in cancer therapy, such as directly depriving glutamine, blocking glutamine transporters, or inhibiting glutaminase activity in cancer cells." (PMID 37249801, 2023). "For this reason, we first measured glutaminase C (GAC) protein expression in different cancer cell lines as well as in HaCaT immortalized keratinocytes." (PMID 37627630, 2023). "Glutamine in cancer cells is catabolized to glutamate with the help of the enzyme glutaminase (GLS/GLS2)." (PMID 37509203, 2023). "Mirroring the effects of inhibitors targeting Complex I and glutaminase or glutamine deprivation, alanine supplementation selectively suppressed OXPHOS in SMARCA4/2-deficient cancer cells." (PMID 37210563, 2023). "The dependence of a plethora of malignancies on glutaminase has prompted the proposition of glutaminase inhibitors as a viable therapeutic strategy for cancer." (PMID 37664031, 2023). "xCT-overexpressing cancer cells are sensitive to glutaminase inhibition because the inhibition of glutamine metabolism decreases GSH production and increases ROS production." (PMID 37842240, 2023). "GLS1 is a kidney isoform of glutaminase, an enzyme that hydrolyzes glutamine to glutamate, which is often upregulated in quickly growing cancer cells to fuel their rapid proliferation." (PMID 37511619, 2023). "Given the role of glutamine in cancer metabolism, GLS has been indicated as a possible target for anticancer therapeutic strategies." (PMID 37627630, 2023).
cancer (continued). "The glutaminase inhibitors compound can inhibit cancer progression via reducing glutamine catabolism." (PMID 37087461, 2023). "Cancer cells rely on glutaminase activity to maintain a high ratio of glutamate to α-ketoglutarate, which is essential for producing non-essential amino acids." (PMID 37241864, 2023). "This process has been suggested as a resistant mechanism for pharmacological glutaminase inhibition in cancer cells." (PMID 36978930, 2023). "Using an orthotopic mouse model for ovarian carcinoma, a reduction in tumor mass, nodules, and metastases was observed by concurrently inhibiting glutamine synthetase in the stroma and glutaminase in cancer cells." (PMID 36902470, 2023). "A mitochondrial enzyme, GLS is often upregulated in the processes of tumorigenesis and tumor development and has been evaluated as a target for cancer treatment." (PMID 37190313, 2023). "This molecule is a potent, non-competitive allosteric inhibitor of the mitochondrial enzyme glutaminase and the only one that is currently being used in Phase I clinical trials in cancer patients." (PMID 37241864, 2023). "As an example, inhibition of GLS (Glutaminase) tends to persuade mitochondrial stress and thus diminution the glycolytic activity in the cancer cells." (PMID 36816957, 2023). "As our results demonstrate that glutamine deprivation induces autophagy, we investigated the therapeutical benefit of a combination of glutaminase inhibitors with the V-ATPase inhibitor archazolid, a known anti-cancer compound that inhibits autophagy." (PMID 37255933, 2023). "In terms of GIST therapy, interesting observations regarding intervention in cancer metabolism were made for glutaminase inhibitors, which were already the object of a clinical trial in GIST (NCT02071862)." (PMID 36774883, 2023). "The race to develop new therapeutics in this field is discussed to provide a reference for developing a novel glutaminase modulator for the treatment of cancers." (PMID 36831355, 2023). "Inhibition of glutaminase activity has become a major focus of academic and pharmacological cancer metabolism research." (PMID 37249801, 2023). "Noteworthy, glutaminase is overexpressed in cancer cells, and this explains why metformin is beneficial for some patients with cancer." (PMID 37626661, 2023). "Glutaminase inhibitors, like CB-839, have displayed efficacy in various cancer models, including lung cancer, by depriving cancer cells of glutamine, an indispensable nutrient for biosynthesis and energy production." (PMID 37880766, 2023). "Although BIS directly stabilizes hexokinase 2 mRNA and glutaminase in cancer cells, the molecular mechanism of defective energy metabolism under BIS depletion is unclear." (PMID 37298584, 2023). "Among the key regulators of glutaminolysis, oxidative phosphorylation (OXPHOS), and the biosynthesis of nucleotides and amino acids, glutaminase (GA, EC 3.5.1.2) has been investigated as a target in many types of cancers." (PMID 36672480, 2023). "The mitochondrial enzyme Glutaminase C (GAC) helps to satisfy this ‘glutamine addiction’ of cancer cells by catalyzing the hydrolysis of glutamine to glutamate, which is then converted to the TCA-cycle intermediate α-ketoglutarate." (PMID 34954143, 2022). "LIAS and PDHB were cuproptosis promoters with low expression in cancer tissues, while GLS and CDKN2A were cuproptosis suppressors with high expression in cancer tissues." (PMID 35875097, 2022). "Inhibiting cancer metabolism via glutaminase (GAC) is a promising strategy to disrupt tumor progression." (PMID 35864951, 2022). "Mitochondrial glutaminase (GLS1) expression is regulated by c-Myc and has gained significant interest in cancer." (PMID 35163079, 2022). "GLS has two isoforms: GLS1 is expressed in many types of cancer, while GLS2 is primarily expressed in the liver." (PMID 36139432, 2022).
cancer (continued). "In fact, glutaminase inhibitors showed anti-proliferative activity in vitro and in vivo in mice in a wide range of cancer models including RCC." (PMID 35223522, 2022). "Activated c-Myc upregulates glutamine metabolism via up-regulation of GLS, making cancer cells dependent on high level of this amino acid to survive and proliferate." (PMID 35593463, 2022). "The expression of cancer-specific isoforms of glutaminase (GLS), a key enzyme of glutaminolysis and responsible for converting glutamine into glutamate, is regulated by the oncogene cMyc." (PMID 36497226, 2022). "The highly selective glutaminase inhibitor CB-839 has been tested in clinical trials for cancer treatment." (PMID 36497226, 2022). "Due to the pivotal role of GLS in glutaminolysis and its influence on multiple inter-related pathways, GLS inhibitors have the potential to exhibit synergistic effects with many cancer therapies that target different pathways." (PMID 36499623, 2022). "Cotargeting of stromal Gln synthetase and cancer cell glutaminase disrupts this metabolic coupling, inducing tumor regression in this setting." (PMID 36115986, 2022). "Currently, no clinical trials evaluate the efficacy and safety of combining glutaminase or arginase inhibitors with immune checkpoint inhibitors in human cancer patients." (PMID 36713558, 2022). "In vitro research has identified higher Gln in cancer stem cells with CD44(+) expression compared to CD44(−), with Gln additionally related to glutamate and Notch signaling via glutaminase, while CD133(+) appears to be linked to Gly." (PMID 35565293, 2022). "Although inhibition of GLS reduces cancer proliferation, we and others have shown that such interventions result in activation of alternative metabolic compensations enabling cancer cell survival under the treatment." (PMID 35158820, 2022). "The oncogenic transcription factor c-Myc enhanced glutaminase production and glutamine metabolism in cancer cells." (PMID 36358687, 2022). "Another example is BPTES [bis-2-(5-phenylacetamido-1, 2, 4-thiadiazol-2-yl) ethyl sulfide], one inhibitor of glutaminase activity, is being explored for anti-cancer characteristics." (PMID 35935878, 2022). "Even though mammalian cells are capable of glutamine production due to the activity of glutamine synthetase (GLUL), some cancer cells require exogenous glutamine, which is catabolized in the mitochondria by another enzyme—glutaminase (GLS)." (PMID 35409206, 2022). "Decreased expression of GLS can reduce glutaminolysis, diminishing the ability to synthesize macromolecules and impairing cell growth and proliferation, especially in cancer." (PMID 35962472, 2022). "The upregulation of glutaminolysis in cancer cells can be attributed to increased activity of glutaminase 1 (GLS1) enzyme." (PMID 36618350, 2022). "Glutaminase1 (GLS1) inhibitor, Bis-2-(5-phenylacetamido-1,3,4-thiadazol-2-yl) ethyl sulphide reduces cancer cell proliferation in vivo." (PMID 36618350, 2022). "The transcription factor c-Myc has been identified as repressing the expression of miR-23a and miR-24b, and that results in the increased expression of glutaminase and the upregulation of glutamine catabolism in cancer cells." (PMID 36013278, 2022). "Cancer cells often overexpress glutaminase enzymes, in particular glutaminase C (GAC), which resides in the mitochondria and catalyzes the hydrolysis of glutamine to glutamate." (PMID 34954143, 2022). "Due to the critical role of glutaminolysis in cancer metabolism, glutaminase has been proposed as a viable target for cancer therapy." (PMID 35053112, 2022). "In cancer, the hydrolysis of glutamine by glutaminase to provide intermediate products for TCA cycle is one of the most well-known complementary pathways." (PMID 35310969, 2022). "Glutaminase 1 (GLS1) is a key enzyme in glutamine metabolism that has been shown to be overexpressed in cancer cell lines and tumor models and to be required for the survival of senescent cells." (PMID 36082022, 2022).
cancer (continued). "This makes GCPII a feasible target for cancer therapy, either alone or in combination with GLS inhibition." (PMID 36499623, 2022). "Considering GLS as a viable therapeutic target because of its role in cancer development, targeting it with the selected hits is an interesting approach." (PMID 35956989, 2022). "Molecules predominantly hampering glutaminolysis by inhibiting glutaminase (GLS), the enzyme catalyzing metabolism of Gln to glutamate, were shown to attenuate cancer growth and proliferation." (PMID 35158820, 2022). "Glutaminase (GLS) plays a crucial role in promoting cell metabolism for cancer cell growth; targeting GLU metabolism by inhibiting GLS has attracted interest as a potential cancer management strategy." (PMID 35956989, 2022). "c-MYC increases cancer cell proliferation by upregulating glutaminase, an enzyme involved in the conversion of glutamine to glutamate." (PMID 35105345, 2022). "Sirt5 plays fundamental roles in supporting cancer cell metabolism by regulating various enzymatic activities and by protecting an enzyme essential for glutaminolysis, glutaminase C (GAC), from degradation." (PMID 35963851, 2022). "A combination of chemotherapeutic drugs with glutaminase inhibitors has recently been exploited to increase the efficacy of cancer treatment." (PMID 36439442, 2022). "This affects the nutritional dependence of cancer cells through glutamine anaplerosis and glutaminase (GLS)." (PMID 36552652, 2022). "GLS (glutaminase) is oncogenic and can influence the metabolic reprogramming of cancer through its functional selective genome and epigenome." (PMID 36620594, 2022). "The inhibitors of GLS in cancer Therapy worked by interfering with the metabolism of alpha-ketoglutarate, an intermediate of the tricarboxylic acid (TCA) cycle, some of which are undergoing clinical trials and exhibiting promising effects." (PMID 36177029, 2022). "GLS is a group of enzymes, whose expression is very frequently alleviated in cancer, which regulates cellular redox homeostasis by fueling the GSH biosynthetic pathway, but also oxidative metabolism by fueling TCA." (PMID 36552620, 2022). "Although the NEAT1-miR-23a-3p association has been reported in other cancers, our data provide a first insight into the roles of NEAT1-miR-23a-3p-GLS axis in cisplatin sensitivity of MB cells." (PMID 35313796, 2022). "Other putative targets include epigenetic regulation enzymes, as well as several metabolites such as adenosine, glutaminase and tryptophan, which are critical players in cancer cell metabolism and in the tumor microenvironment." (PMID 36005167, 2022). "Glutaminase-1 (GLS1), a mitochondrial enzyme that is expressed in most tissues, metabolizes glutamine to glutamate and ammonia to promote cancer cell proliferation primarily through the formation of tricarboxylic acid cycle intermediates." (PMID 35091542, 2022). "Glutaminase 1 (GLS1) hydrolyzes glutamine into glutamate and fuels rapid proliferation of cancer cells." (PMID 36185202, 2022). "Gln is catalyzed in cancer cells by upregulated glutaminase and produces glutamate, which can enter the TCA cycle for ATP generation." (PMID 36115986, 2022). "The other therapeutic option is to use glucose transporters or glutaminase inhibitors to take advantage of the metabolic vulnerability of cancer cells to limit their energy intake." (PMID 35804831, 2022). "GLS has been considered as an attractive molecular target in glutamine metabolism in cancer treatment and tumor therapy." (PMID 36310121, 2022). "Before beginning with the role of the mitochondrial carriers in the aspartate metabolism of cancer cells, it is worth examining glutaminase, the first enzyme in the glutaminolysis pathway through which the majority of aspartate in cancer cells is derived." (PMID 35008407, 2022).
cancer (continued). "Metformin, an antidiabetic drug that was found to have an anticancer effect in multiple malignancies, has a tendency to be more effective against cancer cells that have survived GLS inhibition." (PMID 36499623, 2022). "Targeting glutaminase metabolism by blocking glutaminase has garnered attention as a possible cancer treatment technique, as glutaminase is critical in stimulating cell metabolism during the proliferation of cancer cells." (PMID 36080453, 2022). "Meanwhile, glutamine, which can be transported into cells via transporters, is known to be converted to glutamate and further to α-KG by GDH, GLS and other enzymes for cancer cell growth and proliferation facilitation." (PMID 35272674, 2022). "Removal of the acetyl group induces oligomerization and activation of GLS which reduces oxidative stress in cancer cells therefore promoting their survival." (PMID 35110592, 2022). "One of the possible ways for cancer cells to obtain enough glutamate is by elevating the influx of glutamine into cells followed by enhanced GLS activity." (PMID 36139432, 2022). "The major amino acid whose metabolism is altered in cancer cells is glutamine, as it serves as the source for glutamate and α-ketoglutarate by the action of glutaminase (GLS) enzyme." (PMID 36010595, 2022). "The recent development of high-affinity inhibitors of glutaminase such as CB-839 has led to a flurry of studies on the role of glutaminolysis in sustaining cancer cell growth." (PMID 34172075, 2021). "GLS activity has a correlation with the proliferation of cancer cells, implying that GLS has the potential as a druggable target." (PMID 34354052, 2021). "Inhibiting glutaminase has been shown to restrict tumour growth in both OC and other cancers, as well as sensitizing OC cells to paclitaxel chemotherapy." (PMID 34944851, 2021). "Guiding glutamine metabolism through pharmacological suppression of glutaminase has been converted into many clinical tests as a new cancer treatment." (PMID 34360829, 2021). "MrAII exhibits additional glutaminase activity that can be important to overpower the supportive microenvironment of cancer cells." (PMID 34948436, 2021). "Previously, it was shown that c-MYC regulates mitochondrial glutaminase expression and glutamine metabolism in cancer cells." (PMID 34887764, 2021). "YAP/TAZ regulate the expression of GLS1 (glutaminase) and the aspartate/glutamate transporter SLC1A3, both in tumor cells and in cancer-associated fibroblasts." (PMID 34439395, 2021). "Several glutaminase inhibitors have shown antitumor activity in these glutaminolysis-dependent cancer cells." (PMID 33672789, 2021). "Combinatorial and synergic strategies including glutaminase inhibitors are gaining important battles against cancer." (PMID 33610185, 2021). "The overexpression of glutaminase in cancers helps to fulfil metabolic demand and confers platinum resistance in OC." (PMID 34944851, 2021). "It explains their sensitivity to glutaminase inhibitors because the inhibitors increase metabolic stress in IDH1mt cancer cells." (PMID 33810170, 2021). "Glutamine consumption is often increased in malignant tumors and the inhibition of intracellular glutaminase (GLS) activity – which converts glutamine into glutamate – has been shown to reduce proliferation and angiogenesis of tumor cells of different origin." (PMID 34121995, 2021). "Collectively, our data suggest that EZH2 is a member of the network of cancer metabolism and that EZH2 deficiency upregulates GLS expression and blocks the glucose-deprivation-induced inhibition of GLS transcription in glucose-sensitive cells." (PMID 34671029, 2021). "For instance, the glutaminase inhibitors were effective in reducing the growth of SDH and FH-deficient cancers by lowering the glutamine needed to replenish TCA intermediates including the R-2HG in IDH mutant tumours." (PMID 34070384, 2021).